IL13 (interleukin 13)
Diseases named in the same sentence as IL13 in open-access papers (continued):
Sharing a sentence is not in itself a finding about the gene and the disease.
asthma (continued). "Furthermore, it was found that the levels of TNF-α, IL-1β, IL-4, IL-5, and IL-13 in the BALF, and the levels of IL-17, IL-6, and OVA-specific IgE were observably increased in serum of RSV-infected asthma mice, while the level of IFN-γ was decreased." (PMID 36213326, 2022). "The results of the cytokine contents do not agree with the higher levels of IL-4, IL-5 and IL-13 reported in other asthma models." (PMID 35276769, 2022). "While the isolated blockade of either IL-4 or IL-13 has not been shown to be effective in severe asthma, the dual blockade of IL-4 and IL-13 has been promising." (PMID 35887589, 2022). "Although 30 mg/kg of CCE exhibited the declines of asthma factors such as inflammatory cell count and IL-5, other factors did not observe the significant difference in IL-4, IL-13, OVA-specific IgE, histological analysis and protein expression." (PMID 36034804, 2022). "Interestingly, we found that most of the cytokines (IL-12p70, IL-13, IL-4, IL-6, TNF-α, and IL-8) in the asthma patients tend to increase when the low expression of eosinophils; but in the ACO group, only INF-γ and IL-10 showed an increase." (PMID 36311545, 2022). "TNF-α, IL-13, IL-4, IL-17A and CCL2 are found to increase RhoA mRNA expression via NF-κβ and STAT6 signaling pathways activation, leading to airway hyperreactivity in asthma." (PMID 34069141, 2021). "Wild-type DC10 ablated the OVA-asthma phenotype via induction of Foxp3+ Treg responses, but CD40-/- DC10 had no discernible effects on primary facets of the phenotype (e.g., IL-5, IL-9, IL-13 levels, IgE & IgG1 antibodies; p>0.05) and were ≤40% effective in reversal of others." (PMID 33793599, 2021). "While isolated blockade of either IL-4 or IL-13 has not been shown to be effective in treatment of severe asthma, dual blockade of IL-4 and IL-13 has shown promise." (PMID 35126131, 2021). "Altogether, these results suggest that vaccination with IL-4-K or IL-13-K does not abrogate IL-4 and IL-13 production in this asthma model, but rather induces antibodies that neutralize these cytokines once released." (PMID 33976140, 2021). "Moreover, levels of IL-4, IL-13, and IL-17 in BALF were increases in the asthma group relative to the normal group." (PMID 33577738, 2021). "IL-13 can activate eosinophils, promote IgE secretion, participate in the maintenance of asthma inflammation, and induce small airway remodeling and AHR, which plays an important role in the development of asthma." (PMID 33514798, 2021). "This study aimed to determine whether induced sputum samples can be used for gene expression profiling of T2-high asthma classified by IL4, IL5, and IL13 expression." (PMID 33513844, 2021). "We have evidence that TL1A drives IL13 production by ILC2, which are increased in asthma." (PMID 34305924, 2021). "However, we also identify a number of severe asthma patients, who despite, their therapy have elevated BAL IL‐13." (PMID 33411348, 2021). "Meanwhile, Pts treatment could reduce IL‐4, IL‐13, IL‐5, and IgE (total and OVA specific) levels in the asthma model mice." (PMID 34342160, 2021). "Previous clinical data have shown that atopic and non-atopic asthma patients have higher levels of IL-13 mRNA and IL-13 in sputum and bronchial biopsies than non-asthmatics." (PMID 34439751, 2021). "We have extended our bronchial brush findings of persistent IL‐13 gene expression in the peripheral airways of patients with severe asthma, by demonstrating elevated levels of BAL IL‐13 in patients with severe asthma compared to healthy volunteers and those with mild asthma." (PMID 33411348, 2021). "Indeed, neutralization of both IL-17A and IL-13 inhibited eosinophilia and neutrophilia, mucus hyperplasia, and AHR in a preclinical model of allergen-induced asthma." (PMID 35387016, 2021).
asthma (continued). "Dupilumab, a fully human anti–IL-4α receptor monoclonal antibody, inhibits IL-4 and IL-13 and appears to be effective in patients with moderate to severe asthma, regardless of baseline serum eosinophil counts." (PMID 34829866, 2021). "Th2 cytokines (such as interleukin (IL)-4, IL-5, and IL-13) are produced by CD4+ T cells and are believed to play a key role in asthma pathogenesis by promoting recruitment and activation of mast cells and eosinophils, which are the primary effector cells in the allergic response." (PMID 34356851, 2021). "Various asthma endotypes fall into Th2hi and Th2lo clusters on the basis of the presence or absence of IL-4, IL-5, IL-13 and eosinophils in blood and tissues, respectively." (PMID 34512647, 2021). "ILC2s do not depend on T cells and secrete a large number of type 2 cytokines (such as IL-4, IL5, IL-9, and IL-13) under the function of IL-25, IL-33 and thymic stromal lymphopoietin (TSLP) to participate in asthma, virus infection and worm-host defense related with the type 2 immune response." (PMID 33514798, 2021). "In T2-high asthma, CD4+T helper 2 (Th2) cells and innate lymphoid cells group 2 (ILC2), eosinophils, immunoglobulin E (IgE) and T2 cytokines such as interleukin (IL)-4, IL-5 and IL-13 contribute to its pathogenesis." (PMID 34777398, 2021). "Interrupting IL13 in isolation by genetic deletion or antagonistic blockade reversed established mucus secretion, whereas anti-IL4 blockade did not reduce mucin-secreting goblet cells in a murine model of asthma." (PMID 34305924, 2021). "Experimental study suggests that in allergic or non-allergic asthma, IL-13 will be a very promising target for asthma treatment." (PMID 33514798, 2021). "In addition, MaR1, a DHA-derived SPM, regulated IL-13 release from ILC2 in vitro at nanomolar concentration and in vivo at ng/mouse administration in a murine model of asthma." (PMID 34093589, 2021). "Another IL-13–blocking antibody, tralokinumab, demonstrated neither improvements in asthma symptoms nor reductions in the occurrence of exacerbations." (PMID 34829866, 2021). "Notably, patients with type Th2-high signature asthma consistently show an increased production of MUC5AC,—a process mediated by both IL-13 and epidermal growth factor." (PMID 34943362, 2021). "Importantly, GRK2 expression within T cells is required for the manifestation of characteristic features of asthma such as AHR, airway inflammation, IgE and Th2 cytokine (IL-4 and IL-13) production, goblet cell hyperplasia and mucus secretion." (PMID 35386975, 2021). "We assessed methylation at two asthma-associated genes, IL13 and ORMDL3, in blood samples collected from children with and without asthma and fractionated white blood cell types from healthy adult controls." (PMID 33971943, 2021). "In addition, DPP4 mRNA was shown to be induced by IL-13, indicating the potential role of DPP4 in asthma." (PMID 34955820, 2021). "created a recombinant bifunctional IL-4/IL-13 antagonist that in a mouse of model of asthma reduced not only IL-4–dependent increase in serum IgE levels but also IL-13–dependent airway hyper-responsiveness and lung inflammation." (PMID 34305927, 2021). "Here, we develop conjugate vaccines against mouse IL-4 and IL-13, and demonstrate their prophylactic and therapeutic efficacy in reducing IgE levels, AHR, eosinophilia and mucus production in mouse models of asthma analyzed up to 15 weeks after initial vaccination." (PMID 33976140, 2021). "For example, some asthmatic patients who respond poorly to corticosteroids also do not respond to anti-IL5/anti-IL13 treatments, leaving severe asthma a disease that has no effective cure." (PMID 32300593, 2020). "Although IL-13 regulates a wide spectrum of allergic response in murine models of asthma, anti-IL-13 therapy has not been successful in clinical trials suggesting that blocking IL-13 alone is not effective." (PMID 32477356, 2020).
asthma (continued). "The highest serum IL-4 and IL-13 levels were found in asthma patients, but the intergroup differences were not significant." (PMID 33203095, 2020). "In GSE37693, stimulation of non-asthmatic HBECs with IL-13, mimicking the impact of Th2-inflammation on HBECs, induced a gene signature, that significantly overlapped (60.1%) with our asthma module." (PMID 31969610, 2020). "POSTN functions as the downstream of IL13 and a biomarker for Th2-driven asthma, suggesting that SAE ionocytes may also be related to the pathogenesis of asthma." (PMID 32727470, 2020). "In another study, SIRT1 activator (SIRT1720) treatment decreased the eosinophil count and IL-5 and Il-13 levels, but not IL-4 levels in the bronchoalveolar fluid and lung tissue in the ovalbumin-induced asthma mouse model." (PMID 32823491, 2020). "BAMBI knock out mice model of asthma demonstrated significantly reduced airway hyperresponsiveness, pulmonary inflammation, broncho-alveolar lavage fluid (BALF) eosinophil count, as well as diminished IL-4, IL-5, IL-13 and IL-6." (PMID 32900903, 2020). "The expression level of Vnn1 in lungs was not altered in experimental mouse asthma models challenged by repeated allergen or IL-13." (PMID 32139393, 2020). "Regarding fungi, gut fungal overgrowth (after antibiotic administration or a gut colonization protocol with Candida or Wallemia mellicola) increases the occurrence of asthma via IL-13 without any fungal expansion in the lungs." (PMID 32140452, 2020). "Additionally, this drug inhibits the inflammation of asthma and COPD by suppressing the cytokine expression (i.e., IL-4 and IL-13)." (PMID 31952466, 2020). "Interestingly, increased peripheral blood‐derived fibrocyte CD14 expression following co‐culture is abrogated by IL‐4/IL‐13, which are expressed by mast cells present in the ASM in asthma." (PMID 33209301, 2020). "You22 detected some cytokines in bronchoalveolar lavage fluid (BALF) in asthma model, and OVA and DEHP participated a salient Th2 response which was characterized by the upregulation of Th2-type cytokines, such as IL-4, IL-5 and IL-13." (PMID 32884073, 2020). "Indirect evidence suggested that inhibition of IL-13 did not affect airway wall remodeling, but reduced eosinophilic inflammation in asthma." (PMID 31979396, 2020). "Increased levels of IL5 and IL13 found in MPP children may be connected to the concurrence of MPP and asthma in children." (PMID 31780733, 2019). "Another mAb anti-IL-13 (i.e., tralokinumab, AstraZeneca) failed to reduce asthma exacerbation rate in severe uncontrolled asthmatics." (PMID 31866859, 2019). "IL-4, IL-13, and IL-21, which promoted Th2 differentiation and allergic asthma, were also significantly increased in the CD4+ T cells from the asthma mouse model." (PMID 31231429, 2019). "It has been observed that IL-13 is elevated in COPD, as well as in asthma and other lung diseases." (PMID 31214165, 2019). "Neutralizing IL-13, another Th2 cytokine, has shown promise for treating BHR and airway remodeling in animal models; however, the usefulness of anti-IL-13 antibodies in clinical studies for asthma patients is controversial." (PMID 31216735, 2019). "A randomized, double-blind, placebo controlled study examined the effects of another anti-IL-13 mAb, lebrikizumab (250 mg s.c. once monthly for 6 months), on change in prebronchodilator FEV1 from baseline to week 12 in 219 adults with uncontrolled asthma." (PMID 31866859, 2019). "The intense release of IL-4 and IL-13 in the airways leads to airway narrowing, pulmonary inflammation, airway hyperresponsiveness (AHR), and increased mucus secretion, all typical features of asthma." (PMID 30744098, 2019). "This question is even more intriguing considering that, although IL-4 and IL-13 signaling do not have the same contribution in the pathogenesis of asthma and COPD, in both diseases, pendrin is similarly overexpressed." (PMID 30744098, 2019).
asthma (continued). "Asthma pathogenesis primarily involves activation of eosinophils and CD4+ T cells, with downstream inflammation mediated mainly by Th2-type cytokines (IL-3, IL-4, IL-5, IL-9, IL-13, and granulocyte macrophage colony-stimulating factor)." (PMID 30126769, 2019). "Clinical data have demonstrated that people with atopic and non-atopic asthma have increased concentrations of IL-13 mRNA and IL-13 in sputum samples and bronchial biopsies compared with those without asthma." (PMID 31315668, 2019). "The authors concluded that IL-13 is not crucial for eosinophilic airway inflammation control in patients with moderate-to-severe asthma." (PMID 31866859, 2019). "Interleukin (IL)-4, IL-5, and IL-13, which are canonical type 2 cytokines produced by TH2 cells, prominently mediate the development of asthma and airway inflammation, manifesting as enhanced IgE-mediated sensitization, airway hyperreactivity (AHR), as well as eosinophil infiltration." (PMID 31921177, 2019). "Despite promising findings in several experimental models of allergic inflammation, the results of multicenter studies evaluating the efficacy of anti-IL-13 mAbs in patients with asthma were surprisingly negative." (PMID 31866859, 2019). "In our experiment, Treg cells isolated from patients with asthma expressed higher levels of Th2-type cytokines, such as IL-4, IL-5, and IL-13, rather than IFN-γ, the Th1-type cytokine." (PMID 30013989, 2018). "Lebrikizumab, targeting IL-13 alone with biologics, has not shown a consistent reduction in asthma exacerbation." (PMID 30050954, 2018). "Given that rodents and non-human pimates are used extensively in asthma research, IL-13 effects on AHR were investigated under the same conditions." (PMID 30500834, 2018). "In the present study, we demonstrated that tiotropium bromide improved bronchoconstriction, and that it significantly reduced the concentrations of IL-5, IL-6, IL-13, and KC/CXCL1 in BALF, and subsequently led to reduced neutrophilic airway inflammation in a mouse model of OVA-induced asthma." (PMID 29882826, 2018). "Though IL-5 and IL-13 secretion tended to be higher in those with asthma than in healthy subjects, these differences were not statistically significant." (PMID 30174671, 2018). "Another putative mediator of severe asthma, IL-17F, has been shown to induce IGF-1 expression in bronchial epithelial cells along or by costimulation with IL-4 and IL-13, suggesting an important relationship among IGF-1 signaling, Th2, and Th17 cells in asthma." (PMID 30018981, 2018). "Cellular airway inflammation was absent in the BAL fluid of both WT and IL-13 KO mice, confirming the paucigranulocytic phenotype of this model of chemical-induced asthma." (PMID 28704401, 2017). "Thus the addition of CXCL-1, IFN-γ, IL-5, IL-17A, EGF, eotaxin, IL-lβ, IL-4, IL-12p40, IL-13, and MDC serum concentrations to blood eosinophils and neutrophils adds significant value to the definition of the Difficult-to-Control asthma endotype." (PMID 28686637, 2017). "We did not analyze Th2 cytokines, such as IL-4, IL-5, or IL-13, and therefore we cannot exclude a certain involvement of Th2 response in the regulation of blood coagulation in asthma." (PMID 28429138, 2017). "The treatment with recombinant mouse B7-H3 significantly increased the IL-4 (29.34 ± 4.67 pg/mL), IL-5 (17.64 ± 0.84 pg/mL), IL-13 (421.31 ± 53.60 pg/ml) and IFN-gamma (266.01 ± 32.72 pg/ml) concentration in BALF as compared with mice in the wild-type group with asthma (P < 0.05)." (PMID 28094276, 2017). "Module M31 included the IL-13 response gene, CLCA1 and the mast cell marker carboxypeptidase A3 (CPA3), suggesting a greater expression of mast cell secreted proteases in peripheral airways compared to central airways in severe asthma." (PMID 28045928, 2017).
asthma (continued). "The primary inflammatory lesion of asthma is accompanied by the accumulation of cluster of differentiation 4+ (CD4+) Th2 cells and Eos’s in the airway mucosa and its secretion of a series of cytokines, mostly IL-4, IL-13, IL-5, and IL-9." (PMID 28678189, 2017). "In mouse asthma models that use ovalbumin, house dust mite (HDM), papain, and fungal allergens, ILC2s uniformly increase in number and are the major source of IL-5 or/and IL-13, especially in the early phases of the disease." (PMID 28271447, 2017). "Immunoreactivity of Th2-derived cytokines (IL-4, IL-5 and IL-13) was only weakly detected in the epithelium of nasal biopsy specimens of non-severe asthma patients with CRS (respectively)." (PMID 28199345, 2017). "Increased amounts of IL-13 are observed in the airways of patients with atopic and non-atopic asthma." (PMID 28570692, 2017). "In addition, soluble IL-13Rα2 is effective in blocking the actions of IL-13, including immunoglobulin E (IgE) production, pulmonary eosinophilia, and AHR in animal models of asthma." (PMID 26334389, 2016). "Our finding is in agreement with evidence that IL-13 is a cytokine specifically involved in bronchial hyperreactivity, with a mechanism independent of cell accumulation or airway mucus production." (PMID 28133450, 2016). "IL-13 induces the pathophysiological features of asthma in a manner that is independent of IgE and eosinophils." (PMID 27716424, 2016). "Therefore, while other factors in addition to Th2 cells/cytokines are involved in the pathogenesis of asthma, it appears that WGP is specific in targeting the production of IL-4, IL-5, IL-13 and resulting eosinophilia in this model." (PMID 27390655, 2016). "Extracts of Siegesbeckia glabrescens, a traditional medicinal plant in Korea, reduced mucus overproduction in airways in a asthma murine model, decreased the expression of iNOS and COX-2, reducing the number of inflammatory cells in BALF and the cytokine release (IL-4, IL-5 and IL-13)." (PMID 27445433, 2016). "TRAP-induced asthma is a distinct phenotype of asthma, which was recently shown by our group to be characterized by increased levels of serum IL-17A in children and increased CD4+IL13+IL17+ double-producing T effector memory cells in mice." (PMID 27777592, 2016). "CR‐specific IL‐10 and IL‐13 responses were increased in CR‐sensitive subjects, with or without asthma, whereas asthma alone did not result in increased responses compared to participants without asthma or CR sensitivity." (PMID 27042305, 2016). "Blocking IL-13, but not IL-4, in animal models of asthma prevents the development of AHR after allergen, despite a strong eosinophilic response." (PMID 26334389, 2016). "Therefore, we summarized the miRNAs involved in the pathways common to AR and asthma, such as IL-13, GATA binding protein 3 (GATA-3), and mucin secretion, which have been discovered either in asthma or in the study of AR." (PMID 27187364, 2016). "For example, the median CR‐induced IL‐13 responses were higher in the Atopy (12 pg/mL) and Both (25 pg/mL) populations compared to the Asthma (2 pg/mL) and Neither (2 pg/mL) groups." (PMID 27042305, 2016). "Unlike corticosteroid sensitive patients, systemic prednisolone treatment does not reduce IL-13 production in corticosteroid resistant asthma." (PMID 27716212, 2016). "IL-4 and IL-13 are required for the IgE class switching in B lymphocytes, and increased BAL levels of IL-4 and IL-13 are consistent with elevated allergen-specific IgE in serum and BAL fluid in the sheep asthma model." (PMID 26362930, 2015). "Mucus production by goblet cells in the airway epithelium, a marker of lung remodeling that is also characteristic of asthma and the presence of IL-13, was induced by salmeterol even in the absence of fungus challenge." (PMID 26605551, 2015). "Expression of IL‐5 and IL‐13 was significantly higher among children with asthma, wheeze or mite sensitization compared to those without these features (P < 0.001)." (PMID 26061524, 2015).